MMP9 (matrix metallopeptidase 9)
Diseases named in the same sentence as MMP9 in open-access papers (continued):
Sharing a sentence is not in itself a finding about the gene and the disease.
cancer (continued). "However, curcumin shows a vital role in the inhibition of MMP-9 activities and finally plays a role in the management of cancer." (PMID 25295272, 2014). "A role for Ezh2 in repressing Mmp9 could have implications in the development of therapeutic strategies for cancer." (PMID 25359725, 2014). "The relative amount of MMP-9 mRNA expression differed significantly among the three tissue types (one-way ANOVA, P<0.01), and the fold change in MMP-9 mRNA expression was significantly higher in cancer tissue than in benign tissue or lymph node samples (Tukey's test, P<0.05)." (PMID 24845596, 2014). "Furthermore, TGF-β1 induced the transcriptional activity of NF-κB, which is a transcription factor that regulates MMP-2 and MMP-9 expression, and is well-known to play a role cancer metastasis; KY-05009 also attenuated this effect in a dose-dependent manner." (PMID 25337707, 2014). "SDF-1α stimulates the secretion of MMP-9 in several cancer cells, including MDA-MB-231 cells." (PMID 24887021, 2014). "We have shown that the WAVE3-mediated activation of cancer cell invasion is due, in part, to its regulation of expression and activity of key metalloproteinases (MMPs), including MMP9, which is centrally involved in invadopodia-mediated degradation of the extracellular matrix (ECM)." (PMID 25329315, 2014). "Based on the hypothesis that DLK1-induced cancer cell invasion was mediated by upregulation of MMP9, the expression of MMP9 upon DLK1 stimulation was analyzed by both real-time PCR and Western blotting." (PMID 24621612, 2014). "When combined together, AG14361 and lestaurtinib exhibited a much stronger inhibitory effect on the expression of a number of genes in the NF-κB signaling pathway, such as p50, p65, IL6, IL8, COX2 and MMP9 that are involved in cancer cell proliferation, inflammation, invasion and/or cell death." (PMID 24962108, 2014). "The regulation of both TGF-β and protumorigenic MMPs (e.g., MMP-9) may directly regulate cancer cells growth, angiogenesis, and invasiveness." (PMID 24578639, 2014). "Importantly, the DLL4/Notch/Hey1/MMP9 cascades connecting the endothelium to the cancer cells in metastasis were identified." (PMID 24931473, 2014). "This and our data demonstrate that uPAR and HSP70/MRJ complex may promote matrix degradation, as knockdown of HSP70 and/or MRJ decreased the mRNA levels of mmp2 and mmp9, two important cancer invasion related genes." (PMID 25175595, 2014). "Furthermore, although a soluble secreted enzyme, MMP9 possesses protein-protein binding domains that can serve to tether it to the cancer cell surface, facilitating spatially discrete and directional activities." (PMID 24811362, 2014). "MMP9 is epigenetically regulated by DNA methylation and histone acetylation in cancer cells." (PMID 25359725, 2014). "The expression pattern of MMP-9 was cytoplasmic in both cancer cells and stromal cells." (PMID 24993803, 2014). "In addition, it has been shown that MMP-2 and MMP-9 levels in radical prostatectomy specimens were significant predictors of cancer recurrence." (PMID 24978435, 2014). "The previous data suggest that the wnt/β-catenin pathway may play a role in cancer invasion and metastasis through MMP-9 expression." (PMID 24564183, 2014). "Paradoxically, galectin-7 may also induce the expression of genes known to promote cancer progression, including matrix metalloproteinase-9 (MMP-9) 27,28." (PMID 24515895, 2014). "Instead, MMP-9 is well-known to be secreted from cancer stromal fibroblasts and endothelial cells." (PMID 24586907, 2014). "The results show that ginsenoside Rg1 suppresses PMA-induced NF-κB DNA-binding activity and the phosphorylation of p65, a major component of NF-κB that is known to translocate to the nucleus following phosphorylation and transactivate the promoters of multiple cancer-related genes, including MMP-9." (PMID 25174454, 2014).
cancer (continued). "In addition to EMT, deregulation of the extracellular matrix (ECM) and basement membrane by matrix metalloproteinase (MMPs), such as, MMP2, MMP9 is thought to play a key role in cancer cell invasion and metastasis." (PMID 24885825, 2014). "MMP2 and MMP9 have been shown to play important roles in cancer cell invasion and metastasis." (PMID 24479681, 2014). "Moreover, knocking down EZH2 expression suppresses the cell invasion by downregulating E2F1 and MMP9 in endometrial and in colorectal cancer." (PMID 25295088, 2014). "MMP-9 promotes cancer progression through a variety of mechanisms." (PMID 25274283, 2014). "Interestingly, we and others have shown that WAVE3 can also regulate the expression and activity of these MMPs, suggesting potential role WAVE3/NFκB interplay in the regulation of MMP9 and invadopodia activity in cancer cells." (PMID 25329315, 2014). "Furthermore, our data demonstrated that DLK1 promoted cancer cell invasion through upregulation of MMP9 expression and enhancement of its extracellular activity, which are dependent on the Notch signaling pathway." (PMID 24621612, 2014). "A previous study of the comparative effects of NM, green tea extract and EGCG on the inhibition of MMP-2 and MMP-9 secretion in various cancer cell lines with varying MMP secretion patterns, revealed the superior potency of NM over green tea extract and EGCG at equivalent doses." (PMID 24669274, 2014). "Enhanced production of MMP9 correlates to the invasive phenotype of cancer cells." (PMID 24348851, 2014). "MMP-9 suppresses the proliferation of T lymphocytes through disruption of the IL-2R signalling that may constitute a mechanism of cancer-mediated immunosuppression." (PMID 24713998, 2014). "However, we noted that loss of WAVE3 expression affects the phosphorylation and nuclear translocation of p65, which ultimately led to the inhibition of MMP9 as well as the inhibition of invadopodia formation by cancer cells." (PMID 25329315, 2014). "Moreover, α-mangostin reduced both the mRNA and protein levels of MMP-2 and MMP-9, which play critical roles in migration, invasion, and metastasis of cancer cells." (PMID 24812621, 2014). "FAK inhibition has been shown to reduce MMP-9 secretion in carcinoma cells." (PMID 24667444, 2014). "We next investigated whether elevated levels of MMP-9 protein expression in carcinoma cells could predict the occurrence of metastases, relapse and poor survival rates." (PMID 25151367, 2014). "MMP-9 may have an important role in recurrent/chemoresistant cancer and further investigation of serum MMP-9 is warranted." (PMID 23340649, 2013). "In addition, the MMP9 and uPA are responsible for the degradation of extracellular matrix components and play important roles in the process of cancer invasion and metastasis." (PMID 24274578, 2013). "In fact, MMP-9 has many links to the cancer-related inflammation observed in OSCCs, but MMP-9′s specific role in this process remains unclear." (PMID 23365550, 2013). "While the exact mechanism underlying these changes is not clear, it may be related to the control of MMP expression as Snail2 mediates the upregulation of MMP2 and MMP9 in a range of other cancers." (PMID 23352643, 2013). "Furthermore, the role of MMPs in development of metastasis is well established and the levels of MMP-9 in serum of cancer patients correlate with metastatic potential." (PMID 23936495, 2013). "It was observed that treatment of NSCLC cells with honokiol degraded cytosolic β-catenin, reduced nuclear accumulation of β-catenin and down-regulated matrix metalloproteinase (MMP)-2 and MMP-9, which are the down-stream targets of β-catenin and play a crucial role in cancer cell metastasis." (PMID 23580348, 2013). "MMP2 and MMP9 were identified to exert crucial effect as the indicators in cancer progression." (PMID 24023875, 2013).
cancer (continued). "In addition, MMP-2 and MMP-9 expression levels were found to be significantly lower in the cells treated with combination therapy, indicating that the treatment was controlling cancer cell invasion and metastasis." (PMID 23536878, 2013). "In addition, uPA is a critical enzyme for cancer cell invasion converting plasminogen into plasmin, which degrades extracellular matrix and activates multiple MMPs, including MMP-9." (PMID 23326564, 2013). "Kisspeptin downregulates MMP9 expression in various cancers and this may be the mechanism by which kisspeptin inhibits trophoblast invasion." (PMID 23696833, 2013). "HO1 also augments cancer cell migration and invasion by inducing MMP-9, CD147, and EGFR." (PMID 24180625, 2013). "In particular, the secreted MMP-2 and MMP-9 are important molecules in cancer cell invasion." (PMID 23864892, 2013). "A previous study of the comparative effects of NM, green tea extract and EGCG on inhibition of MMP-2 and MMP-9 secretion of different cancer cell lines with varying MMP secretion patterns, revealed the superior potency of NM over GTE and EGCG at equivalent doses." (PMID 23661254, 2013). "Therefore, MMP-2, MMP-9 and u-PA, which are secreted by invasive cancer cells, are considered to be important in cancer cell invasion and metastasis because of their roles in the degradation of the ECM." (PMID 24039823, 2013). "In OSCC tumors, MMP-9 is expressed in carcinoma and inflammatory cells around carcinoma islands." (PMID 23365550, 2013). "In this study, MMP9 was expressed in both carcinoma cell lines." (PMID 23496982, 2013). "RECK decreases the amount of active MMP-2 and MMP-9 in conditioned medium and inhibits metastatic activity in vitro and in vivo through modulation of these MMPs, which are known to be involved in cancer progression." (PMID 22642976, 2012). "Our gene expression analysis seems to support both hypotheses, as besides CCL2, CCL3 and CCR5 up-regulation, we also observed increased expression of MMP-9 in cancer cells grown under co-culture conditions with macrophages." (PMID 22353646, 2012). "Moreover, sLRP6E1E2 reduced expression of MMP-2/MMP-9, which correlate with tumorigenicity and metastatic potential of cancer cells." (PMID 22606268, 2012). "MMP2 and MMP9 are key enzymes involved in angiogenesis during cancer development." (PMID 23206527, 2012). "The presence of MMP-9 in cancer cells correlated with venous invasion (p=0.0082)." (PMID 22159401, 2012). "Additionally, we have not been able to detect significant levels of either the zymogen or active forms of MMP9 in MSC phenotype in vitro cultures or co-cultures with cancer cells." (PMID 23029122, 2012). "In our study, MMP9 activity was significantly elevated in the PP adipose tissue of overweight/obese men (BMI ≥ 25 Kg/m2), implying excess body fat and the PP fat depot in the modulation of extra-capsular cancer cells' microenvironment." (PMID 22469146, 2012). "However, as with angiogenesis, TSP-1 appears to have dual roles in the regulation of MMP-9 function in cancer, that is, either as a stimulator or an inhibitor." (PMID 22928942, 2012). "By immunohistochemistry, epithelial MMP-9 has been associated with no or ≤2 cm residual disease only if there is a strong signal in a high proportion of cancer cells." (PMID 22200690, 2012). "For example, a previous study of the comparative effects of NM, green tea extract and EGCG on inhibition of MMP-2 and MMP-9 secretion of different cancer cell lines with varying MMP secretion patterns, documented the superior potency of NM over GTE and EGCG at equivalent doses." (PMID 22736175, 2012). "However, recent studies have shown that several members of this family, including MMP9, which were originally recognised as pro-tumourigenic proteases, provide a protective effect in different stages of cancer progression." (PMID 22455335, 2012).
cancer (continued). "CD44 has been shown to anchor the proteolytically-active form of MMP-9 to the cell surface while the constitutive expression of either the transcription factor ID-1 or the receptor DDR1 has been reported to increase the activity of MMP-9 and the invasiveness of human cancer cells." (PMID 21283680, 2011). "Both MMP-2 and MMP-9 play important roles in the pathogenesis of many cancers." (PMID 21909361, 2011). "In malignant tumor, HA may possibly influence the expression of MMP-9 as well as the conversion of the inactive pro-forms to active forms." (PMID 21904555, 2011). "The relation of MMP-9 level to all-cause mortality risk appeared to be driven by a relation to non-cardiovascular mortality risk, but not to cancer mortality risk." (PMID 21283828, 2011). "Only eight carcinomas exhibited bands for the active form of MMP-9." (PMID 21726449, 2011). "Among members of the MMP family, MMP-2 (gelatinase-A) and MMP-9 (gelatinase-B) are particularly up-regulated in malignant tumors and contribute to the invasion and metastatic spread of cancer cells by degrading type IV collagen, a major component of the basement membrane." (PMID 20525232, 2010). "Studies showed that ASA may affect the expression of MMP-9 in cancers through the inhibition of the nuclear localizations of the AP-1 and NF-κB factors." (PMID 20137092, 2010). "Furthermore, NF-κB likely mediates cancer cell invasion, at least in part, by driving MMP-9 transcription." (PMID 20492683, 2010). "The Cancer Pathway Finder Array analysis identified numerous cancer-associated genes exhibiting substantial over expression in trisomic BG01V APCs relative to diploid H9 APCs, including CDC25A, IGF1, MMP9, FGFR2, BRCA1, CASP8 and TERT1." (PMID 20423517, 2010). "In addition, 49 genes have been reported to be relevant to immune diseases, such as CXCL12, COL1A1, MMP9, and CD36, likely reflecting an inflammatory–type response often associated with cancer." (PMID 21060876, 2010). "Like the related invadopodia described in other cancer cells, the podosomes are actin-rich structures closely associated with adhesion molecules and ECM-degrading enzymes such as the matrix metalloproteinases MMP-1, MMP-2 or MMP-9." (PMID 20152043, 2010). "MMP-9 can be produced by cancer or stromal cells but is mostly secreted by macrophages." (PMID 20959825, 2010). "Growing evidence has demonstrated that NGAL can form a complex with MMP-9 and improves MMP-9 expression, prevents its degradation, causing increased MMP-9 enzymatic activity, thereby favoring invasive and metastatic potential of cancer cells in vivo and in vitro." (PMID 19419554, 2009). "This includes actin-binding protein gelsolin a protein involved in cell motility and required for cancer cell invasion, matrix metalloproteases MMP9 which degrade extracellular matrix and promotes invasion, metastasis-associated proteins S100A4/metastasin and cathepsin B (data not shown)." (PMID 19753117, 2009). "As shown by others and in the present study, CD44 expression on the cell surface may define a mechanism for MMP-9 activation and cancer cell migration." (PMID 17343740, 2007). "Therefore, the expected correlation in presence of MMP-8 and MMP-9 was confirmed by the high correlation between both antigen levels (ρ 0.810, P⩽0.001, n=158), and the similar distribution according to the different cancer subgroups." (PMID 16538217, 2006). "Matrix metalloproteinase-8, like MMP-9, is mainly present in neutrophils in carcinomas." (PMID 16538217, 2006). "Thus, although further investigation is required, MMP‐9 inhibition might be counterproductive in late‐stage cancers." (PMID 40556034, 2025). "This dualistic activity reflects the tightly controlled regulation of MMP-9 during angiogenesis, where transient activation facilitates tissue repair, while persistent overexpression drives pathological vascular remodeling in cancer, retinopathy, and chronic inflammatory disorders." (PMID 41304763, 2025).
cancer (continued). "While further studies are needed to elucidate the functional implications of N-glycome remodeling on MMP9 functionality and its role in cancer progression, our findings underscore the importance of this glycoprotein's glycosylation in precise patient stratification and cancer targeting." (PMID 41041068, 2025). "Notably, the recruitment mechanisms (CCL15 vs CXCL5/CXCL1/8) and effector molecules (VEGFC-dominant vs MMP9/VEGFA-cooperative) display cancer-type specificity, suggesting evolutionary selection for distinct molecular implementations of a conserved TANs-lymphatic metastasis principle." (PMID 40739091, 2025). "In addition, evidence suggests that NPRA enhances invasiveness of malignant neoplasm cells by promoting the upregulation of matrix metalloproteinase-9 (MMP9), the mechanism of which may be that NPRA increases MMP9 expression through activation of STAT3." (PMID 40877221, 2025). "In the current study, we hypothesized that MMP9, a potential biomarker for several cancers and a protein with an important role in cancer progression, would be reduced in the AOM/DSS model of colitis‐induced cancer in Gpr4‐deficient animals." (PMID 40397803, 2025). "Furthermore, the functional interplay between Girdin and MMP-9 is critical in cancer progression." (PMID 39851541, 2025). "However, it is important to recognize that the role of MMP9 in cancer is complex." (PMID 40870889, 2025). "We integrated analyzed the function of P4HA3 among 33 types of cancers, and found that P4HA3 was associated with proliferation markers (PCNA and MKI67), EMT markers (VIM, TWIST1, SNAI1, SNAI2, FN1 and CDH2), extracellular matrix (ECM) markers (MMP9, MMP7, MMP2 and MMP14)." (PMID 39504328, 2024). "Moreover, MMP9 was also tend to be expressed in Mono/Macrophage cell in other cancer types." (PMID 38577608, 2024). "Additionally, the anti-proliferative and anti-cancer properties of resveratrol in TNF-β-stimulated HCT 116 cells were associated with the inhibition of various gene products related to cell proliferation, invasion, and survival, such as MMP-9." (PMID 39858430, 2024). "Additionally, MMP9 has been shown to play a role in the development of resistance to chemotherapy, which could have implications for treatment selection in cancer patients." (PMID 38560573, 2024). "Therefore, MMP-9 is considered a promising target for cancer therapy and diagnosis." (PMID 38461536, 2024). "The findings demonstrate that the PAMAM–GA conjugate suppresses the growth of cancer cells originating from various sources, enhances the uptake of GA by cells, hinders colonogenic potential, and limits the migration of cancer cells by downregulating matrix metalloproteinase-9 (MMP-9) expression." (PMID 39339238, 2024). "Additionally, PTK7 could enhance the invasive properties of cancer cells by upregulating MMP9 through activating AP-1 and NF-κB in ESCC." (PMID 39474113, 2024). "Moreover, MMP-9 is critically involved in a variety of diseases, particularly in cancer." (PMID 39712025, 2024). "Furthermore, cancer cell MMP9 was an independent prognostic factor for disease-free survival." (PMID 37296952, 2023). "5-FU-miR-15a was also shown to significantly inhibit the expression of Yap1, Bcl2, Il6, and Mmp9, both alone and during treatment with TGFβ1 in murine and human Pancreatic Stellate Cells, suggesting the reduced proliferation and migration of pancreatic stellate and cancer cells." (PMID 38139352, 2023). "Moreover, COX-2′s role in MMP-9 inhibition indicates its potential as an anti-cancer therapeutic." (PMID 36831374, 2023). "Moreover, morphine as an anti-cancer drug through MMP-9 inhibition shows therapeutic potential." (PMID 36831374, 2023). "In addition, activated platelets secrete lysophosphatidic acid, which upregulates matrix metalloproteinase 2 (MMP2), MMP7, and MMP9 activities in cancer cells, then promote cancer progression by facilitating the detachment of cancer cells from their primary site and into the circulation." (PMID 37153586, 2023).